ZZZ3 (zinc finger ZZ-type containing 3)
Description:
Histone H3 reader that is required for the ATAC complex-mediated maintenance of histone acetylation and gene activation. Component of the ATAC complex, a complex with histone acetyltransferase activity on histones H3 and H4.
Synonyms: DKFZP564I052; ATAC1
Tractability: PROTAC: UniProt records ubiquitination sites on it; ubiquitination databases record sites on it; its protein half-life has been measured.
Gene: Protein-coding gene on chromosome 1 (77,562,416 to 77,683,422, reverse strand). Ensembl gene ENSG00000036549.
Subcellular location: Nucleus
Subcellular location (Human Protein Atlas): Nucleoli; Nucleoli rim; Nucleoplasm
Pathways (Reactome):
Chromatin organization: HATs acetylate histones
Gene expression (Transcription): Formation of WDR5-containing histone-modifying complexes
Gene Ontology:
Molecular function: histone binding; protein binding; zinc ion binding
Biological process: chromatin organization; regulation of cell cycle; regulation of cell division; regulation of DNA-templated transcription; regulation of transcription by RNA polymerase II; regulation of tubulin deacetylation; regulation of embryonic development
Cellular component: ATAC complex; nucleolus; nucleoplasm; mitotic spindle; nucleus
Genetic constraint (gnomAD): Loss-of-function variants: 14 observed, 75.67 expected, observed/expected ratio (o/e) 0.19, 90% interval 0.12 to 0.29. The upper end of that interval is the gene's LOEUF score, 0.29, which puts it in group 1 of 6, group 1 being the genes least tolerant of losing a copy. Missense variants: 806 observed, 1,020.8 expected, observed/expected ratio (o/e) 0.79, 90% interval 0.74 to 0.84. Synonymous variants: 311 observed, 345.75 expected, observed/expected ratio (o/e) 0.9, 90% interval 0.82 to 0.99.
Homologues: Orthologues: chimpanzee ZZZ3 (99% identical), macaque ZZZ3 (99% identical), dog ZZZ3 (96% identical), pig ZZZ3 (94% identical), rabbit ZZZ3 (94% identical), rat Zzz3 (88% identical), mouse Zzz3 (87% identical), guinea pig ZZZ3 (86% identical), tropical clawed frog zzz3 (58% identical), zebrafish zzz3 (49% identical), Drosophila melanogaster Atac1 (15% identical).
Diseases named in the same sentence as ZZZ3 in open-access papers:
ZZZ3 is named in the same sentence as 12 diseases in open-access papers, as found by Europe PMC text mining. Sharing a sentence is not in itself a finding about the gene and the disease. The quoted sentences say what the papers report.
lung adenocarcinoma (1 paper, 2018). A carcinoma that arises from the lung and is characterized by the presence of malignant glandular epithelial cells. "Consistent with the in vitro data, depletion of ZZZ3 by shRNA-mediated knockdown (KD) in H1299 and A549 lung adenocarcinoma cell lines resulted in reduction in global H3K9 and H3K4 acetylation levels." (PMID 30217978, 2018).
lung carcinoma (1 paper, 2017). "To determine whether ZZZ3 also binds to enhancers in lung cancer cells, we further performed ChIP-seq to assess the genome-wide distribution of chromatin marks known to be associated with active promoters (H3K4me3) or with enhancers (H3K4me1) in H1299 cells." (PMID 29057918, 2017).
orchitis (1 paper, 2021). Inflammation of one or both testes due to viral or bacterial infections. "Uqcrb, Sod1, Zfp30, and Zzz3 negatively regulated collagen expression during orchitis." (PMID 35111154, 2021).
sarcoma (1 paper, 2021). A usually aggressive malignant neoplasm of the soft tissue or bone. "Overall survival curves as a function of YEATS2 (I) and ZZZ3 RNA expression (J) across different histological types of sarcoma utilizing RNA-Seq expression data for The Cancer Genome Atlas (TCGA)." (PMID 33913810, 2021). "To determine if expression of YEATS2 and ZZZ3 could be prognostically important in sarcomas other than EHE, we utilized RNA-Seq expression data from sarcoma clinical samples from The Cancer Genome Atlas (TCGA) database." (PMID 33913810, 2021). "Via Kaplan-Meier analysis, we showed that increased expression of YEATS2 or ZZZ3 predicted a poorer prognosis across different histological types of sarcoma, suggesting the ATAC complex may be a key oncogenic driver in multiple sarcomas in addition to EHE." (PMID 33913810, 2021). "In addition, RNA expression profiling data show that expression of YEATS2 and ZZZ3 have prognostic significance in sarcoma clinical samples across various histological types, suggesting that the ATAC complex might represent a key oncogenic driver in other sarcomas." (PMID 33913810, 2021).
virus infection (1 paper, 2021). "No known connection between virus infection and ZZZ3 exists, but it may serve a critical role in regulating gene expression in response to general infection." (PMID 34051754, 2021).
adenocarcinoma (1 paper, 2024). A common cancer characterized by the presence of malignant glandular cells. "Here, we focused on ZZZ3, a protein shown to be implicated in regulating genes encoding ribosomal proteins in mESCs and human adenocarcinoma cells." (PMID 38701777, 2024).
ZZZ3 also shares sentences with these, for which no sentence is quoted: Buruli ulcer (1 paper); cervical cancer (1); diffuse large B-cell lymphoma (1); infection (1); Obesity (1); tumor (1).